VIRMA (vir like m6A methyltransferase associated)
Diseases named in the same sentence as VIRMA in open-access papers (continued):
Sharing a sentence is not in itself a finding about the gene and the disease.
cancer (86 papers, 2019 to 2026). A tumor composed of atypical neoplastic, often pleomorphic cells that invade other tissues. "Studies reveal VIRMA’s pan-cancer significance, with aberrant overexpression observed in over 20 cancer types that associate with chromosome 8q21.3-24.3 amplification." (PMID 40723784, 2025). "VIRMA (vir-like m6A methyltransferase associated) is known to promote the progression of cancer and is associated with poor survival in multiple types of cancer." (PMID 39457524, 2024). "Most of them proposed the oncogenic potential of VIRMA from loss of function studies, whereby VIRMA depletion resulted in attenuation of cancer growth and/or metastasis." (PMID 37208522, 2023). "We show one network consisting of 12 genes including ANKLE2, SHROOM3 and ELFN2 interacting through direct connections with VIRMA, a nuclear/cytosolic protein involved in RNA methylation/adenylation and implicated in different cancers." (PMID 35619151, 2022). "Among cell cycle-related proteins, CDK1 acts as an oncogene in cancers and is most associated with VIRMA in different breast cells." (PMID 33731118, 2021). "The data included in this review suggested that VIRMA is mainly upregulated in various cancer types, and is associated with poor survival." (PMID 33731118, 2021). "As a required component and the largest methyltransferase, vir-like m6A methyltransferase associated (VIRMA) can promote the progression of cancer and is associated with poor survival in multiple types of cancer." (PMID 33731118, 2021). "In addition, VIRMA can promote the progression of cancer and is associated with poor survival in multiple types of cancer." (PMID 36077287, 2022). "Thus, aberrantly expressed VIRMA may alter m6A methylation of many more transcripts than aberrantly expressed core m6A methyltransferases to cause human diseases, including cancer." (PMID 37208522, 2023). "This review summarizes the role of VIRMA in malignant tumors from multiple perspectives and explores its potential applications in clinical diagnosis and treatment." (PMID 40723784, 2025). "VIRMA, the largest and evolutionarily conserved core of the m6A methyltransferase complex, is highly expressed in the embryonic brain and various cancers." (PMID 40577453, 2025). "The m6A modification mediated by VIRMA in regulating ferroptosis is a promising area of further exploration in treating cancer and overcoming cancer resistance." (PMID 40723784, 2025). "Multiple studies have showcased elevated VIRMA levels in various cancers, including breast, colorectal, and non–small cell lung carcinoma." (PMID 40577453, 2025). "Nevertheless, KIAA1429, also thought to be VIRMA (vir‐like m6A methyltransferase‐associated protein), is a renowned subtype of m6A methyltransferase in human cancers and has been found to be carcinogenic in many cancers." (PMID 38585432, 2024). "When the genomic alterations are investigated, most of the m6A regulators harbor SNVs across different cancers, with ZC3H13, VIRMA, and PRRC2A having higher mutation frequencies." (PMID 39457524, 2024). "Most of the m6A regulators are found to be mutated across the cancers, with ZC3H13, VIRMA, and PRRC2A having a higher frequency rate." (PMID 39457524, 2024). "In summary, we have uncovered the m6A-associated role of VIRMA in breast tumourigenesis via the long non-coding RNA, NEAT1 and have shed light on the potential role of VIRMA in determining the fate of cancer cells under stress." (PMID 37208522, 2023). "In the present study, we have identified a previously unreported contribution of the lncRNA, NEAT1, to cancer cell proliferation via VIRMA-mediated m6A methylation." (PMID 37208522, 2023). "VIRMA has been found to serve an oncogenic role in several cancers, and was found to promote resistance to apoptosis in HCC." (PMID 35350378, 2022). "VIRMA is dysregulated in several cancer types, influencing cell proliferation in both a m6A-dependent and a m6A-independent manner." (PMID 34950106, 2021).
cancer (continued). "While the roles of m6A modifications in cancers have been extensively reviewed elsewhere, the crucial functions of VIRMA in various types of cancer, as well as the potential targeting of VIRMA as cancer treatment, have not yet been highlighted." (PMID 33731118, 2021). "The obvious oncogenic roles of VIRMA observed in different types of cancer and the mechanisms of VIRMA promoting cancers provided the basis for potential therapeutic targeting for cancer treatments." (PMID 33731118, 2021). "Using the Gene Set Enrichment Analysis (GSEA), we found that IGF2BP1, VIRMA, and ZC3H13 are all associated with pathways in cancer and WNT signaling pathway." (PMID 32950970, 2020). "The expression of VIRMA and associated levels of global m6A methylation in DU145 and PC-3 cancer cells were significantly higher compared to normal prostate cells (p = 0.0434 and p = 0.0298, respectively)." (PMID 32218194, 2020). "Future approaches may include targeted knockout or silencing of VIRMA using nanoparticle delivery systems, offering new possibilities for cancer treatment." (PMID 40723784, 2025). "We demonstrate that VIRMA-mediated m6A plays a crucial role in regulating the turnover of transcripts involved in ribosome biogenesis, thereby maintaining active ribosome biogenesis during normal brain development and potentially in some cancers as well." (PMID 40577453, 2025). "We observed similar ribosome biogenesis defects in VIRMA-depleted cancer cells." (PMID 40577453, 2025). "As one of the m6A writers, VIRMA also affects the progression of malignant tumors." (PMID 41256854, 2025). "Moreover, numerous recent studies have reported up-regulation of VIRMA in various human cancer types." (PMID 40577453, 2025). "Future research may focus on exploring the direct interaction mechanisms between VIRMA and cell cycle-related proteins to deepen the understanding of the connection between VIRMA and cancer." (PMID 40723784, 2025). "In summary, our findings reveal the essential role of VIRMA-mediated m6A modification in adapting the protein synthesis machinery by controlling ribosome biogenesis in actively proliferating cells, in both brain development and cancer." (PMID 40577453, 2025). "In HNSCC, VIRMA facilitated cancer progression by modulating the m6A levels of UBR5." (PMID 40723784, 2025). "Similarly, in OSCC, silencing VIRMA upregulated the concentrations of Fe2+ and lipid ROS, promoting ferroptosis in cancer cells." (PMID 40723784, 2025). "Among them, VIRMA was found to occupy the largest known component in the readers, indicating that VIRMA might have various functions and play a crucial role in cancer pathways." (PMID 38577917, 2024). "ZC3H13, VIRMA, and PRRC2A almost have a higher mutation frequency rate in all cancer types." (PMID 39457524, 2024). "Our study identifies oncogenic VIRMA overexpression as a vulnerability that may be exploited for cancer therapy." (PMID 37208522, 2023). "More importantly, the increased sensitivity of full-length VIRMA-overexpressing cancer cells to prolonged UPR presents a vulnerability that may be exploited for therapy." (PMID 37208522, 2023). "In addition, we also noticed that VIRMA was upregulated in different types of cancer based on The Cancer Genome Atlas data." (PMID 37028765, 2023). "Moreover, immunohistochemical staining in 110 human ICC patients and normal adjacent tissues revealed that VIRMA expression was significantly higher in ICC cancer compared to the adjacent counterparts." (PMID 36691046, 2023). "It is tantalising to speculate that the full-length VIRMA isoform will exert an m6A-dependent role in cancer development and maintenance." (PMID 37208522, 2023). "Understanding the involvement of distinct VIRMA isoforms in tumourigenesis is important in determining whether there is one predominant isoform that contributes to cancer development." (PMID 37208522, 2023). "The oncogenic role of VIRMA in several cancers is covered elsewhere in detail." (PMID 35350378, 2022).
cancer (continued). "Generally, VIRMA is an oncogene in most types of cancer, and downregulating it could inhibit cancer progression, indicating that VIRMA can become a diagnostic/prognostic biomarker in certain cancer types." (PMID 33731118, 2021). "VIRMA is also upregulated and promote cancer progression in HCC." (PMID 33731118, 2021). "Inhibiting these downstream targets could reverse the oncogenic effect of VIRMA in cancer progression." (PMID 33731118, 2021). "The obvious oncogenic roles of VIRMA observed in these cancer types suggested that VIRMA may serve as a potential therapeutic target in cancer treatment." (PMID 33731118, 2021). "The present review investigated the role of VIRMA in various types of cancer." (PMID 33731118, 2021). "Besides that, HNRNPA2B1, YTHDC1, METTL14, WTAP, and ZC3H13 were downregulated in cancer tissues, whereas VIRMA had opposite alterations between these two databases." (PMID 33225598, 2021). "As regards the regulatory role of VIRMA in cancer, it was found that, in addition to the m6A-dependent pathway, VIRMA could also regulate downstream m6A-independent pathways." (PMID 33731118, 2021). "Furthermore, VIRMA also promoted cancer progression in an m6A-independent manner in CRC." (PMID 40723784, 2025). "Therefore, it is worth exploring whether up-regulated VIRMA in cancer cells orchestrates ribosome biogenesis." (PMID 40577453, 2025). "Our focus on VIRMA, a scaffolding protein that stabilizes the m6A writer complex, has yielded substantial evidence that aberrant expression of an auxiliary m6A writer protein may affect tumourigenesis and cancer cell survival." (PMID 37208522, 2023). "VIRMA was found to be correlated with the most positive oncogenic pathways among the ‘writers’, indicating that VIRMA may has multiple different functions and plays important roles in cancer pathways." (PMID 33731118, 2021). "Thus, inhibiting VIRMA and these downstream targets are considered potent cancer therapies." (PMID 33731118, 2021). "The expression of VIRMA may also be regulated by miR-143-3p in cancer cells." (PMID 33731118, 2021). "Knockdown of VIRMA could inhibit cancer cell proliferation and metastasis in vitro." (PMID 33731118, 2021). "Indeed, our previous observations highlighted frequent VIRMA upregulation in primary TGCTs (which was also confirmed in an independent study analyzing multiple cancer types), with strong VIRMA immunoexpression found in 72.4% of samples and, in particular, in 84.2% of metastatic patient samples." (PMID 34446080, 2021). "In NPC, VIRMA mediated m6A modification of PTGS2, enhancing its mRNA stability and promoting cancer progression." (PMID 40723784, 2025). "To address this, we examined two cancer cell lines, MCF7 and HeLa, using shRNA knockdown to investigate the impact of VIRMA suppression on ribosome biogenesis." (PMID 40577453, 2025). "VIRMA was lactylated in CRC cells, and its lactylation levels were significantly elevated in cancer cells incubated with CAF‐derived exosomes." (PMID 41017455, 2025). "To determine the effect of VIRMA overexpression on cancer cell survival following enhanced UPR activation and ER stress, we compared the viability of VIRMA FL-overexpressing and control cells exposed to increasing doses of Thapsigargin for 48 h." (PMID 37208522, 2023). "Remarkably, when comparing BlCa with NUT, we found that not only METTL14 but also METTL3, VIRMA, and ALKBH5 expression was significantly decreased in cancer tissues." (PMID 35048498, 2022). "For the three selected regulators, IGF2BP1, VIRMA, and ZC3H13, the GSEA study result indicated that they were also all correlated with pathways in cancer and WNT signaling pathways." (PMID 32950970, 2020). "Moreover, significant positive correlations between VIRMA or IGF2BP3 protein expression and ANLN protein expression were observed in human pan-cancers." (PMID 41513610, 2026).
cancer (continued). "Furthermore, in LUAD, VIRMA has been demonstrated to regulate the expression of the oncogene MUC3A through an m6A-dependent mechanism and promote cancer progression." (PMID 40723784, 2025). "Genes NOG, TGFB1, VIRMA, and SRC were over-expressed in cancer." (PMID 40724805, 2025). "While studies have shown that VIRMA overexpression promotes growth and/or metastasis in cancers, it was not clear which isoforms of VIRMA are ectopically overexpressed." (PMID 37208522, 2023). "In OSCC, VIRMA regulated PGK1 via the YTHDF1/m6A-dependent pathway, leading to increased glucose uptake, lactate production, and extracellular acidification rate (ECAR), with decreased oxygen consumption rate (OCR), ultimately enhancing the glycolytic rate and capacity of cancer cells." (PMID 40723784, 2025). "In conclusion, akin to METTL3, METTL4, METTL16, WTAP, RBM15/15B, VIRMA, and ZC3H13, the potential influence of YTHDC1, YTHDC2, YTHDF, IGF2BPs, the HNRNP family, eIF3, FTO, and ALKBH3/5 on autophagy is intertwined with their roles in RNA metabolism, collectively regulating autophagy in cancer." (PMID 38148841, 2023). "Although the regulatory subunits of the m6A writers WTAP, VIRMA, ZC3H13, and HAKAI have been reported to be associated with cancers, whether their functional roles in cancers are dependent on m6A modification is not reported." (PMID 32245947, 2020). "METTL3 knockdown could decrease CDK1 mRNAs with m6A modification, while VIRMA knockdown did not change the level of m6A modification in CDK1 mRNAs, indicating that m6A modification did not disturb the interaction between VIRMA and CDK1 in cancer cells." (PMID 33731118, 2021).
infection (2 papers, 2019 to 2021). The state of being infected such as from the introduction of a foreign agent such as serum, vaccine, antigenic substance or organism. "Transcriptome analyses showed that infection with influenza A virus upregulated the expression level of WTAP (two of six experiments) but downregulated METTL3, RBM15, and VIRMA (one of six experiments, each)." (PMID 34502037, 2021).
VIRMA also shares sentences with these, for which no sentence is quoted: germ cell tumor (6 papers); clear cell renal cell carcinoma (4); asthma (3); breast invasive carcinoma (3); esophageal squamous cell carcinoma (3); head and neck squamous cell carcinoma (3); lung squamous cell carcinoma (3); Stomach Adenocarcinoma (3); cardiovascular system diseases (2); childhood asthma (2); chronic myeloid leukemia (2); colorectal tumor (2); embryonal carcinoma (2); Infertility (2); metastatic disease (2); multiple myeloma (2); pancreatic adenocarcinoma (2); rectal adenocarcinoma (2); uterine corpus endometrial carcinoma (2); acute myeloid leukemia (1); adenomyosis (1); autoimmune thyroid disease (1); B cell lymphoma (1); breast tumors (1); colorectal adenocarcinoma (1); cutaneous melanoma (1); endometrial adenocarcinoma (1); esophageal adenocarcinoma (1); esophageal carcinoma (1); head and neck cancer (1).
A further 31 diseases each share a sentence with VIRMA in 1 paper.